CLC (Charcot-Leyden crystal galectin)
Description:
Regulates immune responses through the recognition of cell-surface glycans. Essential for the anergy and suppressive function of CD25-positive regulatory T-cells (Treg).
Synonyms: Gal-10; LGALS10; LGALS10A; MGC149659; GAL10; LPPL_HUMAN
Tractability: Small molecule: a structure with a bound ligand is known. PROTAC: its protein half-life has been measured.
Gene: Protein-coding gene on chromosome 19 (39,731,255 to 39,738,029, reverse strand). Ensembl gene ENSG00000105205.
Subcellular location: Cytoplasm, cytosol; Cytoplasmic granule
Gene Ontology:
Molecular function: identical protein binding; phosphatidylcholine lysophospholipase activity; protein binding; carbohydrate binding
Biological process: regulation of activated T cell proliferation; regulation of T cell anergy; regulation of T cell cytokine production; T cell apoptotic process
Cellular component: cytosol; extracellular matrix
Genetic constraint (gnomAD): Loss-of-function variants: 15 observed, 13.58 expected, observed/expected ratio (o/e) 1.1, 90% interval 0.74 to 1.67. The upper end of that interval is the gene's LOEUF score, 1.67, which puts it in group 6 of 6, group 1 being the genes least tolerant of losing a copy. Missense variants: 158 observed, 173.79 expected, observed/expected ratio (o/e) 0.91, 90% interval 0.8 to 1.04. Synonymous variants: 68 observed, 61.91 expected, observed/expected ratio (o/e) 1.1, 90% interval 0.9 to 1.34.
Homologues: Orthologues: pig LGALS13 (54% identical), rabbit CLC (51% identical), Caenorhabditis elegans lec-1 (26% identical), Caenorhabditis elegans lec-3 (25% identical), Drosophila melanogaster galectin (25% identical), zebrafish lgals3b (24% identical), zebrafish si:dkey-95h12.2 (24% identical), Caenorhabditis elegans C27C7.5 (23% identical), Caenorhabditis elegans lec-12 (20% identical), Caenorhabditis elegans lec-6 (20% identical), Drosophila melanogaster CG11374 (18% identical), Drosophila melanogaster CG13950 (18% identical), and 13 more. Paralogues in human: LGALS13 (54% identical), LGALS16 (52% identical), LGALS14 (49% identical), LGALS4 (27% identical), LGALS7 (27% identical), LGALS7B (27% identical), LGALS3 (24% identical), LGALS8 (24% identical), LGALS9 (22% identical), LGALS9B (22% identical), LGALS9C (22% identical), GRIFIN (20% identical), and 4 more.
Diseases named in the same sentence as CLC in open-access papers:
CLC is named in the same sentence as 98 diseases in open-access papers, as found by Europe PMC text mining. Sharing a sentence is not in itself a finding about the gene and the disease. The quoted sentences say what the papers report.
asthma (32 papers, 2012 to 2026). "Some studies have identified CLC/Gal‐10 as a potential biomarker of eosinophil engagement in allergic rhinitis, asthma, and other diseases associated with eosinophil activation." (PMID 37283884, 2023). "This association does not persist after adjusting for eosinophil count, likely because the mechanisms by which CLC genetic variants and expression influence IgE concentration—and presumably asthma and allergic diseases—are mediated by eosinophils." (PMID 36793728, 2023). "Lower DNAm of CLC, a gene for lysophospholipase expressed in eosinophils, was associated with current asthma, allergic asthma, and FeNO." (PMID 31300640, 2019). "It has been reported that glutathione (GSH), which targets CLCs, disrupts Gal‐10 CLC formation and inhibits the crystallization of human Gal‐10 by chemically modifying Cys57, thereby ameliorating asthma symptoms." (PMID 41568067, 2026). "Prior studies have identified increased CLC protein levels in induced sputum as a surrogate biomarker of eosinophilic airway inflammation in asthma." (PMID 36793728, 2023). "Asthma and AR share eight common genes (CLC, EMR4P, IL5RA, FRRS1, HRH4, SLC29A1, SIGLEC8, IL1RL1) that are presumed to describe the link for multimorbidity." (PMID 36825519, 2023). "Another recent study used a humanized mouse model of asthma to demonstrate that administration of CLC protein with house dust mites (HDM) increased human IgE synthesis compared to when HDM was administered alone." (PMID 36793728, 2023). "Discovered DMRs annotated to genes implicated in allergy and asthma, Th2 activation and eosinophilia (EPX, IL4, IL13, PRG2, CLC and ZFMP1) and genes previously associated with asthma and IgE in an EWAS of blood (ACOT7, SLC25A25)." (PMID 35344303, 2022). "In the asthma cohort, Charcot-Leyden crystal galectin (CLC) revealed the most prominent downregulation in expression in the benralizumab-treated arm across all patients, as well as for eosinophil-high and eosinophil-low patients (> 4-fold, FDR < 0.05)." (PMID 30658649, 2019). "Adding dupilumab to IL-13-treated cell cultures partially restored cilia in asthma patients, indicating that enhancing CLC function may help explain the therapy’s benefits." (PMID 41303221, 2025). "In children with asthma, we found an FGL2-driven subnetwork for B cell proliferation and T cell activation associated with both PM2.5 and ozone exposure; a CLC- and CPA3-driven subnetwork for leukocyte differentiation associated with ozone; and a TNFRSF10C-driven subnetwork associated with PM2.5." (PMID 41430723, 2025). "Among the differentially co-expressed genes, eight were previously linked to asthma in genome- (MRPL14, ASB3, RHOBTB2) and epigenome-wide (CLC, EPS15, GPI, SSCRB4, STRN4) association studies and five were mentioned in the literature in the context of asthma (SLC19A1, MAEA, CLC, ATP1B1, and RECK)." (PMID 36835202, 2023). "Moreover, the differentially co-expressed genes, both up- and down-regulated in EA, were previously linked to asthma in the genome- (e.g., MRPL14, ASB3, RHOBTB2) and epigenome-wide (e.g., CLC, EPS15, GPI, SRCRB4D, STRN4) association studies." (PMID 36835202, 2023). "Furthermore, CLC/Gal-10 has been detected in celiac disease, asthma and other allergic diseases, as well as in hypereosinophilic syndrome (HES)." (PMID 34209362, 2021). "We found that CLC and S100A13 were among the top genes showing differential expression in airway epithelium in asthma." (PMID 36793728, 2023). "For example, a Gal-10-specific antibody blocked CLC autocrystallization and relieved the inflammation in a humanized mouse model of asthma." (PMID 36838965, 2023). "In another report, eight genes (CLC, EMR4P, IL5RA, FRRS1, HRH4, SLC29A1, SIGLEC8, IL1RL1) were consistently overexpressed in all types of multimorbidity for asthma, dermatitis, and rhinitis." (PMID 36291593, 2022).
asthma (continued). "Functional gene categories represented in DMRs and individual CpGs found for FeNO, asthma, and allergy were eosinophilic activity (EPX, CLC, PRG2), and Th2 responses (IL-4, ZFPM1)." (PMID 31300640, 2019). "CST1, CLC, FETUB and VSMT1 were upregulated in asthma and allergic diseases in nasal studies, which could reflect overrepresentation of allergic diseases in our non-TB control group." (PMID 41542684, 2026). "Both the six gene signature (6GS: CPA3, DNASE1L3, CLC, IL1B, ALPL, and CXCR2) and T‐helper 2 signature (TH2S: CLCA1, SERPINB2, and POSTN) are proposed as biomarkers in the identification of inflammatory phenotypes of asthma in induced sputum and epithelial brushings, respectively." (PMID 31903716, 2020). "A six-gene signature (CLC, CPA3, DNASE1L3, IL1B, ALPL, and CXCR2) can differentiate asthma patients from controls, discriminate inflammatory phenotypes of asthma and predict the ICS response, but this method is not currently available." (PMID 30598830, 2018).
allergic disease (10 papers, 2015 to 2026). An immune response that occurs following re-exposure to an innocuous antigen, and that requires the presence of existing antibodies against that antigen. "We found that the levels of expression of genes involved in allergy development and innate immunity, including those encoding CLC, MS4A3, DEFA3, DEFA4, IL8RA, and IL8RB, were lower in PBMCs from IgG4-RD patients than from healthy controls." (PMID 25973893, 2015). "The expression of genes related to allergy or innate immunity, including CLC, MS4A3, DEFA3, DEFA4, IL8RA and IL8RB, was lower in PBMCs from patients with IgG4-RD than from healthy controls." (PMID 25973893, 2015). "Until recently, the functional role of CLC/galectin-10 in allergic diseases remained unknown." (PMID 36291593, 2022).
allergic rhinitis (7 papers, 2012 to 2023). Inflammation of the nasal mucous membranes caused by an IgE-mediated response to external allergens. "CLC/Gal-10 is a potentially useful biomarker of eosinophil/basophil involvement in asthma, allergic rhinitis and other eosinophil-associated inflammatory diseases." (PMID 26904159, 2016). "A bioinformatics study showed that homozygotes for the minor allele of single nucleotide polymorphisms in the CLC promoter region may regulate Gal-10 expression and thus might cause allergic rhinitis." (PMID 30424011, 2018). "Galectin-10 or Charcot Leyden crystal protein (CLC) has been previously related with the inflammatory process and, recently also, it has been found in patients with allergic rhinitis." (PMID 22654612, 2012). "However, without in vitro and/or in vivo experiments to correlate Gal-10 crystallization to dairy-free diets, we cannot simply recommend dairy-free diets for patients with bronchial asthma, seasonal allergic rhinitis, or other CLC-related diseases." (PMID 36838965, 2023).
eosinophilia (6 papers, 2012 to 2025). "Most cases in Europe and North America are labeled with a chronic type 2 inflammatory response with tissue eosinophilia and significantly elevated levels of tissue expression of IL-5 and CLC." (PMID 38978039, 2024). "Also, the analyses of post-mortem RNA-sequencing with COVID-19-infected lungs versus normal controls show the significant expression and upregulation of genes related to eosinophilia, such as CLC (Galectin-10), RNASE2 (EDN), and CCL11 (eotaxin-1)." (PMID 40710346, 2025).
nasal polyps (5 papers, 2012 to 2024). "Chronic rhinosinusitis with or without nasal polyps displays variable degrees of eosinophilic and neutrophilic inflammation, with a profound neutrophilic infiltration and activation in type 2 inflammation, associated with eosinophil extracellular trap cell death and CLC accumulation." (PMID 36838965, 2023).
bronchiectasis (3 papers, 2012 to 2024). Segmental, irreversible dilation of the bronchial tree resulting in the accumulation of secretions which leads to obstruction. "A similar pattern was observed for CLC in patients with bronchiectasis, but again this was not statistically significant after correcting for multiple comparisons." (PMID 37780108, 2023).
COVID-19 (3 papers, 2021 to 2025). A disease caused by infection with severe acute respiratory syndrome coronavirus 2. "Given reports of eosinopenia in COVID-19 patients, we were surprised to find that multiple eosinophil-associated granule genes were significantly upregulated in COVID-19 patient lung tissue, for example CLC (Galectin-10) and RNASE2 (EDN)." (PMID 33777047, 2021). "Interestingly, our gene expression analysis of post-mortem COVID-19 patient lungs revealed that the eosinophil associated genes, CLC, RNASE2 (EDN), and CCL11 were some of the most upregulated genes in COVID-19 lung tissue." (PMID 33777047, 2021). "Although EDN and CLC are most abundantly expressed in eosinophils, they have also been found in other leukocytes, albeit at much lower quantities, which may account for the increased expression seen in COVID-19 patient samples." (PMID 33777047, 2021).
Dent disease (3 papers, 2020 to 2025). Dent disease is a rare genetic renal tubular disease characterized by manifestations of proximal tubule dysfunction. "Despite certain limitations, our findings regarding the multiple changes in CLC-mediated Cl−/H+ shifts caused by disease-related variants underscore the need for future studies to further enhance our understanding of the molecular genetic basis of Dent disease." (PMID 40420588, 2025). "Genetic variants have been associated with several human diseases including developmental encephalopathies (ClC‐3 and ClC‐4), Dent's disease (ClC‐5), and osteopetrosis (ClC‐7)." (PMID 40568930, 2025).
epilepsy (3 papers, 2020 to 2024). A brain disorder characterized by episodes of abnormally increased neuronal discharge resulting in transient episodes of sensory or motor neurological dysfunction, or psychic dysfunction. "However, despite its limitations, our description of multiple changes in CLC-mediated Cl–/H+ exchange by disease-associated mutations represents a first step toward understanding the molecular basis of X-linked intellectual disability and epilepsy." (PMID 35721313, 2022). "Voltage-gated chloride channels (ClC) participate in the epileptogenesis process of epilepsy, and the inhibition of ClC may have anti-epileptic effect." (PMID 38300446, 2024).
osteopetrosis (3 papers, 2020 to 2025). Osteopetrosis, also known as marble bone disease, is a descriptive term that refers to a group of rare, heritable disorders of the skeleton characterized by increased bone density on radiographs. "However, neither the patients nor a mouse model that carried the equivalent mutation developed osteopetrosis, although expression of ClC-7Y715C induced the formation of enlarged intracellular vacuoles." (PMID 38136669, 2023).
deafness (2 papers, 2017 to 2020). An inherited or acquired condition characterized by the complete loss of the ability to hear from one or both ears. "However, ClC-Kb must be able to compensate for a loss of ClC-Ka as the sole loss of ClC-Ka does not lead to deafness as indicated by a large cohort." (PMID 28555110, 2017).
inflammatory bowel disease (2 papers, 2022 to 2025). A spectrum of small and large bowel inflammatory diseases of unknown etiology. "On the other hand, CLC is typically expressed in eosinophils, and its increase is typically associated with altered epithelial barrier functions, including food-allergic enteropathies and inflammatory bowel diseases." (PMID 35625760, 2022).
leukemia (2 papers, 2022). A malignant (clonal) hematologic disorder, involving hematopoietic stem cells and characterized by the presence of primitive or atypical myeloid or lymphoid cells in the bone marrow and the blood. "In our in vitro study, the gene and protein expression of p16 and phosphorylated pRb were examined simultaneously in eight canine lymphoma and leukemia cell lines (17-71, CLBL-1, GL-1, CLC, CLGL-90, Ema, Nody-1, and UL-1)." (PMID 36006308, 2022).
myeloid leukemia (2 papers, 2010 to 2022). A clonal proliferation of myeloid cells and their precursors in the bone marrow, peripheral blood, and spleen. "The CLC protein (Charcot-Leyden crystal protein/Galectin-10) is a lysophospholipase in the galectin super family of proteins, normally expressed in eosinophils and basophils, associated with inflammation and some myeloid leukemia." (PMID 20459617, 2010).
retinal degeneration (2 papers, 2009 to 2020). Degeneration of the retina. "It will therefore be of interest to analyze expression of CLF-1 in the physiologic and pathophysiological mouse retina to investigate the biologic significance of elevated CLC expression levels during light-induced retinal degeneration." (PMID 19693290, 2009).
Alzheimer disease (1 paper, 2020). A progressive, neurodegenerative disease characterized by loss of function and death of nerve cells in several areas of the brain leading to loss of cognitive function such as memory and language. "This would be the case of genes such as POU4F1 for Alzheimer's disease or CLC for schizophrenia." (PMID 32392208, 2020).
B cell lymphoma (1 paper, 2020). "The antibody also bound dose-dependently to the canine B cell lymphoma cell line CLBL-1, but not to other canine lymphoma cell lines: GL-1, CL-1, Ema, UL-1, CLC, CLK, CLGL90, and 17–71 cell lines (data not shown)." (PMID 32651429, 2020).
bronchiolitis (1 paper, 2006). Inflammation of the bronchioles characterized by swelling of the bronchioles and mucus accumulation. "The present study identified the genes IFI27 and CLC to be highly differentially expressed in whole blood of infants hospitalised with RSV, subtype B, bronchiolitis of moderate severity." (PMID 17166282, 2006). "We found the interferon, alpha-inducible protein 27 (IFI27) and Charcot-Leyden crystal protein (CLC) to be the most differentially expressed genes in this study and not to be reported before in conjunction with acute viral bronchiolitis." (PMID 17166282, 2006). "The gene IFI27 is upregulated and the gene CLC is downregulated in whole blood of infants hospitalised with RSV, subtype B, bronchiolitis and is not reported before." (PMID 17166282, 2006).
Cognitive impairment (1 paper, 2019). Abnormal cognition is characterized by deficits in thinking, reasoning, or remembering. "We explored the function of the Drosophila ClC‐a chloride channel, since its mammalian ortholog CLCN2 is expressed in glial cells, and defective channel function results in leukodystrophies, which in humans are accompanied by cognitive impairment." (PMID 31479171, 2019).
developmental delay (1 paper, 2020). "A study showed CLC proteins (including CLC‐5 encoded by the CLCN5 gene) could regulate electrical excitability of neurons, thus, the relationship between developmental delay and CLCN5 mutations may exist." (PMID 32495484, 2020).
disc degeneration (1 paper, 2025). "Strikingly, by 14 months, Smo‐deficient mice exhibited significantly accelerated disc degeneration associated with increased CLC production in the NP." (PMID 40977276, 2025). "However, their conclusion was based on only two CLC‐resident discs, which may did not have Krt19− C‐CLCs and D‐CLCs, since these two CLC subtypes most likely form at later stages of disc degeneration." (PMID 40977276, 2025).
Hyponatremia (1 paper, 2026). An abnormally decreased sodium concentration in the blood. "Hyponatremia is a prevalent disorder marked by excess water retention and substantial morbidity, motivating interest in the CLC-Ka chloride channel as a therapeutic target." (PMID 41756880, 2026).
lysosomal storage disease (1 paper, 2017). A metabolic disorder caused by mutations in proteins critical for lysosomal function, including lysosomal enzymes, lysosomal integral membrane proteins, and proteins involved in the post-translational modification and trafficking of lysosomal proteins. "However, although ClC-7unc mice presented neuronal cell loss and lysosomal storage disease similar to the ClC-KO mice, the osteopetrotic phenotype was partially rescued by the presence of pure Cl- currents." (PMID 28386229, 2017). "In the case of ClC proteins, impaired function of ClC-1, ClC-2, ClC-K, ClC-5, and ClC-7 may result in myotonia congenita, azoospermia/leukodystrophy, Bartter syndromes types 3 and 4, Dent’s disease, and osteopetrosis/retinal degeneration/lysosomal storage disease, respectively." (PMID 28386229, 2017).
neuroblastoma (1 paper, 2013). Neuroblastoma (NB) is the most common solid, extracranial childhood tumor. "Because inhibition of signaling by the CLC/CLF receptor has previously been connected to oxidative stress, we chose to focus on CRLF1 as a potential mediator of oxidative stress resistance during differentiation of neuroblastoma cells." (PMID 23818941, 2013). "Together these data indicate that signaling of secreted, soluble CLC/CLF through gp130 and JAK kinases is dispensible for resistance to 6-OHDA in neuroblastoma cells regardless of their differentiation state." (PMID 23818941, 2013).
RSV bronchiolitis (1 paper, 2006). "However, the possible importance of CLC downregulation in peripheral blood of infants with RSV bronchiolitis need more studies." (PMID 17166282, 2006).
schizophrenia (1 paper, 2020). A major psychotic disorder characterized by abnormalities in the perception or expression of reality. "The situation is even more complex in the case of MPC2, CLC, and HIST1H2AC, which are all associated with schizophrenia." (PMID 32392208, 2020).